KRAS (KRas proto-oncogene, GTPase)
Diseases named in the same sentence as KRAS in open-access papers (continued):
Sharing a sentence is not in itself a finding about the gene and the disease.
cancer (continued). "In the phase I trial, 84 patients with KRAS G12C-mutated advanced cancers received LY3537982 monotherapy." (PMID 37569406, 2023). "In contrast, KRAS mutations were associated with KRAS amplifications, suggesting a synergistic role in driving cancer proliferation." (PMID 36980591, 2023). "In our study, we found that cancer cells display distinct oncogenic alterations in the two risk groups (e.g., KRAS, PIK3CA, mTOR) that appear to directly induce metabolic changes." (PMID 36671486, 2023). "Because of the KRAS-variants’ association with KRAS, there has been extensive study of the impact of cetuximab on patients with cancer with the KRAS-variant." (PMID 37728512, 2023). "Drugs such as Sotorosib have promising anti-cancer activity in KRAS G12C mutated advanced solid cancers." (PMID 36831055, 2023). "KRAS mutations are prevalent in many cancers including pancreatic, breast, colon, and lung with mutational hotspots at G12 (89%), G13 (9%), and Q61 (1%) residues." (PMID 37396909, 2023). "Numerous studies have shown that KRAS mutations can have an impact on the prognoses of cancer patients, although the results of different studies are somewhat contradictory regarding their specific impacts." (PMID 36675641, 2023). "Since the discovery of mutations in the KRAS gene in the early 1980s, many researchers have worked on targeting this protein to effectively treat cancer." (PMID 37376135, 2023). "It is the most mutated oncogene in human cancers, which hinders the development of effective drugs against KRAS." (PMID 37568193, 2023). "The RAF-ERK and PI3K-AKT pathways are two major hyper-activated downstream pathways in KRAS mutation, which induce the uncontrolled proliferation of cancer cells and metastasis in cancer patients." (PMID 37174108, 2023). "Another example of mutational differences produced in cancers of different origins is the KRAS gene." (PMID 37174676, 2023). "We observed from the UMAP plot that KRAS mutations have a certain degree of impact on specific cell types, especially epithelial (malignant tumor) and fibroblast populations." (PMID 37954616, 2023). "This work constitutes a first step towards the implementation of new combinatorial approaches involving RT and MRTX1257 in KRAS G12C mutated cancers, with the aim of providing new therapeutic strategies with a prolonged clinical benefit." (PMID 37907934, 2023). "For example, pancreatic cancer, with a 5-year survival rate of less than 5%, is one of the most lethal cancers caused by a mutation of the KRAS gene with rapid development and a poor prognosis." (PMID 38026850, 2023). "Several selective inhibitors of MEK and ERK have been developed as potential agents to combat KRAS-mutated cancers." (PMID 37996408, 2023). "Mutated KRAS plays a key role in the generation and development of various cancers, thereby becoming a promising target in anti-cancer drug development." (PMID 37110848, 2023). "VS-6766 (Avutometinib) is a dual RAF–MEK inhibitor that showed good therapeutic activity against KRAS G12V mutation and is under clinical evaluation (NCT03875820, Phase I, NCT04625270, Phase II) for different types of KRAS-mutated cancers." (PMID 37376135, 2023). "In CORE cancers, we found that 3 out of the 93 tumors with KRAS mutations were predicted to be resistant to KRAS depletion." (PMID 37141389, 2023). "Oncogenic KRAS mutations have been found in a variety of cancers, including LC, colon cancer, and pancreatic cancer." (PMID 37111737, 2023).
cancer (continued). "Functional analyses demonstrated that gain-of-function mutations in p110α confer the ability to interact with KRAS, forming a complex responsible for the enhanced oncogenic activity of cancer cells." (PMID 37759534, 2023). "Previous studies have reported that p21 is closely related to KRAS mutation, cancer cell migration, invasion, proliferation, and cell cycle and the epithelial-mesenchymal transition of PC cells." (PMID 37182151, 2023). "Understanding how KRAS mutations drive cancer pathogenesis and developing new interventional strategies are the major priorities for conquering KRAS-driven cancers." (PMID 36413402, 2023). "RTK-driven feedback activation widely exists in KRAS-mutant cancer cells, and this pathway feedback activation is mediated through mutant KRAS, at least for the G12C, G12D, G12V variants." (PMID 37808191, 2023). "RAN is a protein regulating the rate of nucleocytoplasmic shuttling, and cancer possessing KRAS activating mutation, c-Met enhancement, and PTEN-deletion are more sensitive to apoptosis induced by silencing RAN." (PMID 36834736, 2023). "Conversely, prevalence of KRAS mutations is higher in histologically normal endometrium compared to corresponding cancer." (PMID 37573406, 2023). "Tumors that harbor KRAS mutations are highly aggressive and are associated with poor prognosis and resistance to cancer therapies." (PMID 38051103, 2023). "In various cancers, mutations in the KRAS gene have been linked to poor prognosis and a limited range of targeted treatment options." (PMID 38105263, 2023). "Since cancer-driver mutations (KRAS, ARID1A, PIK3CA) are similar in deep lesions and endometriomas, tumorigenesis results from additional factors." (PMID 36979957, 2023). "KRASG12C with a high incidence in cancers such as non‐small cell carcinoma is a common type of KRAS mutation." (PMID 37250144, 2023). "Regarding vaccines, an mRNA-based cancer vaccine (V941) targeting KRAS mutations (G12D, G12V, G12C, and G13D) is under clinical trials to treat solid tumors (NCT03948763, Phase I)." (PMID 37376135, 2023). "KRAS is the most frequently mutated oncogene in human cancers, yet strategies targeting its downstream signaling kinases have failed to produce durable treatment responses." (PMID 37961649, 2023). "KRAS is one of the most studied and challenging targets in cancer research, mainly due to the enormous difficulty of treating KRAS-mutated cancers." (PMID 37376135, 2023). "Typical examples of PBD-containing PIDRs in the Ras superfamily include the plasma membrane (PM) associated KRAS4B (hereafter KRAS) and RhoA whose mutation or overexpression is known to cause cancers." (PMID 37919400, 2023). "Type II EC exhibits KRAS mutation and studies have shown that the expression profiles of miR-181b, miR-324–3p, and miR-518b are decreased in cancer with a KRAS mutation." (PMID 37663424, 2023). "Mutations in STK11, CDKN2B, KEAP1, CTNNB1, MET, and KRAS were associated with a significantly increased risk of cancer-associated thrombosis." (PMID 38069251, 2023). "For example, bioinformatics analysis of RAS and CIP2A-regulated phosphoproteomes revealed a significant overlap in their functional pathways, and strong synergies between CIP2A and RAS expression or KRAS mutation in cancer cell growth and survival were found." (PMID 37170215, 2023). "In particular, oncogenic KRAS mutations drive glucose uptake and utilization via metabolic reprogramming to support cancer cell growth, which enhances the flux of glucose to the HBP and glycolytic biosynthetic branches." (PMID 38093368, 2023). "Investigating the mechanisms underlying immunotherapy resistance in KRAS-mutant cancers is an important area for future research." (PMID 37662925, 2023).
cancer (continued). "Abnormal activation of KRAS proteins strongly stimulates signals associated with various cancer-related processes in CRC, including cell proliferation, migration and neoangiogenesis." (PMID 37509241, 2023). "A significantly greater proportion of HRAS-mutant cancers (48.4%) were found to have co-altered mutations along the RTK/MAPK/PI3K pathways compared to KRAS- (41.4%) and NRAS-mutant (38.4%) cancers (p<0.05 for both)." (PMID 37503077, 2023). "Both reduced cell proliferation, but the sensitivities differed among different KRAS-mutated cancer cells." (PMID 37662925, 2023). "The mechanistic basis linking Ras isoforms, Ras dosage and cancer mutation patterns was potentially provided by the observation that the KRAS gene is enriched in rare codons." (PMID 36864243, 2023). "As the most frequently mutated oncogene in human cancer, KRAS has been established as a paradigm for targeting Ras proteins and other small GTPases." (PMID 37221195, 2023). "The increased abundance of SGs associated with KRAS mutation is linked to stress resistance properties in cancer cells; thus, SGs are potential biomarkers for tumor fitness and drug responses." (PMID 37705755, 2023). "KRAS-mutated oncogenes are reported to be more likely to develop cancer-related diseases, and more than 11% of all cancers are defined as a result of mutation in the KRAS gene, which is a growing health concern." (PMID 38026850, 2023). "Different strategies based on nanotechnology to deliver small chemical molecules, as well as biomolecules and advanced therapies, including gene therapy, have been proposed to treat KRAS-mutated cancers." (PMID 37376135, 2023). "Among these (e.g., patients 16–24), some were indeed cancer cells that displayed point mutations in the KRAS and PIK3CA genes (Pt." (PMID 36672711, 2023). "As these inhibitors largely target the active pathways, their activities are not limited to individual point mutations, potentially treating a larger cohort of patients with a KRAS-mutated cancer." (PMID 37190303, 2023). "A synergism of the CAIX-associated regulatory pathways and the mutant KRAS oncogenic signaling most likely contributes to therapy resistance and survival of residual cancer." (PMID 36768903, 2023). "A significant reduction in KRAS mutation levels in cancer cells, leading to a notable antitumor effect." (PMID 38045808, 2023). "Several other Phase 1, 2, and 3 trials are further evaluating the efficacy and safety of single agent Adagrasib and in combination with Docetaxel, Palbociclib, Cetuximab, BI 1701963, and TNO155 in KRAS G12C mutated cancers." (PMID 37190303, 2023). "For example, regarding metabolic rewiring, KRAS-mutated cancer cells possess a high endocytic activity mainly via micropinocytosis to allow a high intake of nutrients." (PMID 37376135, 2023). "RAS mutation is the most frequent oncogenic alteration in human cancers, and KRAS is the most frequently mutated followed by NRAS." (PMID 36583506, 2023). "As a result, inhibitions of upstream effectors, such as HER3 and other ErbB receptors, have little effect on cancer cells with KRAS mutations." (PMID 37163206, 2023). "The recent FDA approval of drugs that selectively target KRAS G12C is a significant accomplishment that has a major impact on patients with cancer whose tumors harbor KRAS G12C mutations." (PMID 38051103, 2023). "9d induced SOS1 degradation in various KRAS-mutated cancer cells and displayed higher antiproliferation activity compared to the parent SOS1 agonist." (PMID 38023987, 2023). "Similar to activating KRAS mutations, the amplification of wild-type KRAS seems to constitute an alternative means of activating this oncoprotein in cancer." (PMID 37569406, 2023).
cancer (continued). "Five clinical trials have already begun evaluating this combination in KRAS-mutated solid cancers, with data to date suggesting this is a promising avenue for indirect targeting of KRAS-mutated cancers." (PMID 37190303, 2023). "Activating mutations of KRAS are among the most common driver mutations in human cancers, leading to aberrant signaling and hyperactivation within the MAPK pathway." (PMID 37108538, 2023). "For example, the mutation of KRAS leads to the resistant to gefitinib, erlotinib and cetuximab which induce the apoptosis of cancer cells in the therapy of cancer." (PMID 37368936, 2023). "Based on these considerations, we propose that combined induction of ferroptosis and FSP1 inhibition should be considered for therapeutic strategies developed against KRAS-mutated cancers." (PMID 36443441, 2023). "KRAS mutations are observed across a variety of cancer entities, while the recent advent of the KRAS (G12C) inhibitor render KRAS-mutant tumors druggable." (PMID 37760445, 2023). "KRAS mutations are among the most common gene mutations in tumors, causing uncontrolled cell proliferation and thus a high risk of cancer, and are associated with pancreatic, lung, and colon cancers." (PMID 37514088, 2023). "Regarding fatty acid synthase (FASN), increased expression is often reported in many different cancer types and has in fact been linked to gemcitabine resistance in KRAS mutated PDAC." (PMID 36675307, 2023). "Other molecular hallmark signatures observed in Group 4 include the cancer progression-related pathways (coagulation and KRAS signaling)." (PMID 37334114, 2023). "In contrast, patients with CRC have shown much lower susceptibility to the same treatment, suggesting a diverse dependency of KRAS-mutant cancers on specific KRAS mutant alleles." (PMID 37020035, 2023). "KRAS mutations are among the most common drivers of human cancer and are associated with tumorigenesis and poor prognosis." (PMID 36694209, 2023). "According to the COSMIC database for somatic mutations in cancer, mutations on the 12th amino acid of the oncogene KRAS are amongst the most common mutations across all cancers." (PMID 37591832, 2023). "KRAS gene mutations are often linked with poor response to treatment and increased risk of cancer recurrence with a low survival rate." (PMID 37240273, 2023). "Within CIN-subtype GEA, the oncogene KRAS, which is renowned for activation by missense mutation in many cancers, is recurrently subject to focal high-level amplification without mutation." (PMID 36752207, 2023). "KRAS has emerged as the most common mutation in human cancers amongst the three RAS isoforms, and KRAS activation occurs early at the very beginning of endometrial carcinogenesis." (PMID 37663424, 2023). "One of the most important ongoing first-in-human trials is the SHERPA trial, a combination therapy of SHP2 inhibitor RMC-4630 and ERK inhibitor LY3214996 in metastatic KRAS-mutated cancers." (PMID 37569406, 2023). "Due to the high prevalence of KRAS mutations in human cancers, these mutations have become a major focus for countless researchers for over forty years." (PMID 37108538, 2023). "KRAS mutations have been shown to increase proteasome capacity and activity to promote cancer cell survival." (PMID 36923647, 2023). "PTPN2 is reported to regulate the activation of KRAS mutations, as well as the proliferation and survival of cancer cells, making it a potential therapeutic target for KRAS-mutant cancers." (PMID 36675641, 2023). "KRAS mutations are among the most frequent gain-of-function alterations found in patients with cancer and their therapeutic targeting has long been a key objective in precision oncology." (PMID 37258666, 2023). "The understanding of this resistance mechanism is challenging due to the intracellular heterogeneity and variability of KRAS G12C-mutated cancer cells." (PMID 37396909, 2023).
cancer (continued). "We suggest that KRAS is the most frequently mutated Ras isoform in cancer in part because it has a higher level of expression that is closer to the sweet-spot compared to the other isoforms." (PMID 36864243, 2023). "KRAS is regarded as a major oncogenic promoter in various cancers, and KRAS mutations have been frequently detected in PC and CRC." (PMID 36834334, 2023). "KRAS is one of the most commonly mutated proteins in cancer, and efforts to directly inhibit its function have been continuing for decades." (PMID 37258666, 2023). "NSCLC has a 5-year survival rate of approximately 25 %, and KRAS mutation has been shown to be associated with radioresistance and decreased cancer-specific survival after lung stereotactic RT." (PMID 36313934, 2023). "Detailed analysis of the false-positive cancer calls reveals that most are due to a specific KRAS G12V variant: chr12:25,245,350 C > A." (PMID 37121998, 2023). "The most widely studied mode of action for mutated KRAS is the cell‐intrinsic mechanism involved in human cancer pathogenesis." (PMID 36599679, 2023). "For several years, KRAS was considered an untargetable and undruggable target, and KRAS-mutated cancer was considered untreatable." (PMID 37376135, 2023). "KRAS oncoproteins have long been considered undruggable targets, limiting the therapeutic options of cancer patients with KRAS mutations to standard cytotoxic treatments." (PMID 36928090, 2023). "Both studies have shown that cancers with KRAS mutations rely on resistance mechanisms that involve signaling through the ERBB network." (PMID 37314501, 2023). "This successfully sensitized the cancer cells to gefitinib through GAB1-SHP2 dissociation, disabling the feedback loop between Ras and AKT pathways and causing 70% loss in cell viability of KRAS-mutant NCI-H23 NSCLC cancer cells." (PMID 36865093, 2023). "Functionality experiments also showed that silencing KRAS can reverse the cancer-promoting effect caused by overexpression of hsa_circ_0001846." (PMID 38081815, 2023). "Given previous studies, we postulated the KRAS variants that are activating and repurposing targeted inhibitors previously used for cancer would allow us to test and precisely identify molecularly targeted novel therapeutics." (PMID 37154160, 2023). "RAS superfamily of G-proteins genes is the most frequently mutated in cancers accounting for up to 30% of human tumors, with KRAS being the most rampantly mutated, accounting for up to 86% of RAS mutations in cancer." (PMID 36961909, 2023). "Although KRAS is one of the most frequent mutated oncogenes in cancer, mutations in KRAS appear at low frequency in ALL patients at diagnosis." (PMID 36674902, 2023). "KRAS is a potential oncogene and has been reported to have a high mutation rate, which makes cancer cells escape apoptosis-induced cell death." (PMID 37189139, 2023). "Given that KRAS is predominantly mutated in cancers harboring RAS mutations, drug development targeting NRAS mutations lags far behind and remains an unmet medical need." (PMID 37083947, 2023). "Until recently, KRAS (KRAS proto-oncogene) mutations in cancers were thought to be “undruggable”, but novel small molecule inhibitors have now been developed that can specifically target the KRASG12C mutations." (PMID 37370858, 2023). "While direct KRAS inhibitors have already shown synergistic effects with immunotherapy, these novel methods pave the way to potentially treat a larger cohort of KRAS-mutated cancers." (PMID 37190303, 2023). "As expected, we found that patients with KRAS mutations from all cancer types had significantly lower prediction scores, indicating higher KRAS dependency, which was also seen in all CCLE tissue types." (PMID 37141389, 2023). "In the context of KRAS-mutant cancer, NF1 loss usually indicates overactivation of RAS and enhanced cell growth." (PMID 37355626, 2023).